AGER (advanced glycosylation end-product specific receptor)
Diseases named in the same sentence as AGER in open-access papers (continued):
Sharing a sentence is not in itself a finding about the gene and the disease.
atherosclerosis (24 papers, 2006 to 2026). A disease characterized by the build-up of fatty material and calcium deposition in the arterial wall resulting in partial or complete occlusion of the arterial lumen. "Advanced glycosylation end product-specific receptor (AGER) signaling has been implicated in atherosclerosis." (PMID 26226616, 2015). "Consistent with this rs1035798:C>T, a non-coding single nucleotide polymorphism (SNP) in the AGER gene, has been associated with clinically significant manifestations of atherosclerosis, such as ischemic stroke." (PMID 26226616, 2015). "The activation of AGER can evoke a wide range of signaling pathways that trigger inflammation, atherogenesis and vasoconstriction leading to coronary dysfunction, atherosclerosis and thrombosis." (PMID 23894685, 2013). "The three most promising proteins (CELSR2, FN1, and SPARCL1) were identified as potential therapeutic targets for atherosclerosis, while APOE, LPA, APOA5, TGFB1, and AGER also hold potential as drug targets for the disease." (PMID 40649979, 2025). "It is possible that rs1035798:C>T influences the balance between AGER isoforms in atherosclerosis, however, this study does not identify a clear mechanism by which this SNP is associated with fatal CV events." (PMID 26226616, 2015).
Alzheimer disease (23 papers, 2018 to 2025). A progressive, neurodegenerative disease characterized by loss of function and death of nerve cells in several areas of the brain leading to loss of cognitive function such as memory and language. "Finally, a study on Alzheimer's disease also showed that AGER and HMC variants were in synergy to be associated in such pathology as it is also the case in chronic fatigue syndrome." (PMID 30863465, 2019). "In Alzheimer’s disease, AGER contributes to the accumulation of amyloid-beta plaques and the activation of microglia, which can exacerbate neuroinflammation and neuronal damage." (PMID 37965040, 2023). "To address the role of AGER in caspase-11 inflammasome activation, we first used FPS-ZM1, a high-affinity AGER-specific inhibitor identified from high-throughput screenings in an experimental model of Alzheimer's disease." (PMID 31440260, 2019). "FPS-ZM1 is a blood-brain barrier permeant, non-toxic, and high affinity AGER-specific inhibitor used in experimental chronic obstructive pulmonary disease (COPD) and Alzheimer's disease." (PMID 31440260, 2019).
lung carcinoma (23 papers, 2011 to 2025). "Interestingly, low expression AGER was associated with poor overall survive (OS) only in American Joint Committee on Cancer (AJCC) stage T2 of lung cancer patients." (PMID 37497166, 2023). "In addition, genetic polymorphisms of AGER have been reported to increase risks of lung cancer and breast cancer." (PMID 34026765, 2021). "Furthermore, several genetic mutations in AGER are responsible for lung cancer development." (PMID 36067196, 2022). "However, the association between the AGER polymorphisms and the risk of lung cancer might depend on ethnicity." (PMID 29212235, 2017). "The two signatures show an overlap of four genes (EMP2, AGER, STX11, GYPE) with two of them known to be linked to lung carcinoma." (PMID 38993634, 2024). "We investigated the Kaplan–Meier plotter and PrognoScan database for the prognostic feature of AGER expression in lung cancer." (PMID 37497166, 2023). "Overall, the downregulation of AGER implies the critical role in the occurrence and development of lung cancer." (PMID 37497166, 2023). "During the occurrence and metastasis of lung cancer, AGER‘s significance has been demonstrated in the progression, angiogenesis, and immune cell infiltration mediated by lysophosphatidic acid." (PMID 37497166, 2023). "The results showed that SPP1, SLC2A1 was significantly highly expressed in the lung cancer cell, while AGER was in the opposite." (PMID 36782138, 2023). "AGER has also been directly shown to have inhibitory effects on the development of lung cancer and is a potentially favorable prognostic marker for NSCLC." (PMID 36358600, 2022). "Previous studies have shown that AGER is downregulated in lung cancer and exhibits tumor suppression function." (PMID 35372081, 2022). "Accumulating evidence has shown the downregulation of AGER in lung cancer, leading to enhanced proliferation, invasion and migration abilities, and decreased apoptosis of cells." (PMID 34026765, 2021). "AGER protein expression has been shown to be increased in the lungs of smokers with COPD whilst decreased in human lung cancer cell lines." (PMID 21304900, 2011). "Advanced glycosylation end product specific receptor (AGER), which recognizes endogenous molecules released during chronic inflammation, is one of the innate immune pattern recognition receptors abnormally overexpressed in lung cancer." (PMID 38713284, 2024). "This indicates that AGER could potentially be targeted for immune-related therapy in cases of lung cancer." (PMID 37497166, 2023). "The data suggest that different expression levels of AGER may affect the immune infiltration cells of diverse subtypes of lung cancer, such as LUAD and LUSC, ultimately influencing their prognosis." (PMID 37497166, 2023). "By contrast, lncRNA advanced glycosylation end-product specific receptor (lncAGER) could strengthen the effect of human monocytes against lung cancer, thereby inhibiting tumor migration and growth." (PMID 29368602, 2018). "AGER expression is significantly decreased in human lung carcinomas, which suggests that AGER may function in suppressing lung cancer." (PMID 23741331, 2013). "The role of AGER now requires further elucidation in the lung which may provide new insight into the mechanisms underlying several lung diseases where AGER genetic variants have been implicated, including e.g. COPD and lung cancer." (PMID 27755550, 2016). "Especially, five lung cancer-related genes including CYP4B1, CHRDL1, SFTPC, SFTPB, and AGER were consistently downregulated in both LUAD and LUSC had a positive correlation with TMPRSS2, exhibited an opposite effect on the prognosis of LUAD and LUSC." (PMID 35082790, 2021). "As AGER and ANGPTL7 both show strong links to cancer, it is plausible that their interacted gene ATP13A4-AS1 also engages in the progression of lung cancer by exerting similar impacts on cellular activities." (PMID 34026765, 2021).
lung carcinoma (continued). "SPP1, AGER, and RTKN2 regulate the lung cancer-related pathways such as VEGF (vascular endothelial growth factor) signaling pathway and NF-kappaB." (PMID 30453959, 2018). "Then, low AGER expression was obviously related with poor OS in lung cancer patients with negative surgical margins." (PMID 37497166, 2023). "However, unlike other cancers, AGER is down-regulated in NSCLC and also supported by the previous finding suggested its role as a tumor suppressor in lung cancer." (PMID 31681566, 2019).
pancreatic cancer (20 papers, 2012 to 2024). "Recent studies have demonstrated that oxidative stress increases the activity of NF-κB which upregulates the expression of AGER in pancreatic cancer." (PMID 25197670, 2014). "ROS can increase the release of HMGB1 from necrotic cells and then activates Beclin-1-dependent autophagy by binding to AGER in pancreatic cancer cells." (PMID 25197670, 2014). "Pancreatic cancer cells may release KRAS-G12D by binding to advanced glycation end-product-specific receptors (AGER) during ferroptosis." (PMID 37598126, 2023). "Furthermore, they found that KRASG12D is released in exosomes during the ferroptosis of pancreatic cancer cells with KRASG12D mutation and is uptaken by macrophages via advanced glycosylation end product-specific receptor (AGER)." (PMID 35372083, 2022). "Additionally, pancreatic cancer cells release KRAS-G12D via exosomes during ferroptosis, and macrophages then take up these KRAS-G12D and undergo M2 polarization mediated by AGER to promote tumor progression." (PMID 35444656, 2022).
emphysema (18 papers, 2016 to 2025). "This was the first study to simultaneously elucidate the associations among emphysema, sRAGE, and polymorphisms of the AGER gene." (PMID 35144588, 2022). "RAGE (encoded by AGER) has been implicated as a driver of cigarette smoke related emphysema, and circulating sRAGE has been implicated as a biomarker for emphysema." (PMID 35331221, 2022). "We aimed to analyse the association between sRAGE levels and emphysema according to the genotypes of rs2070600 in the AGER gene." (PMID 35144588, 2022). "Among the multiple variants of AGER, rs2070600 is a particularly notable sentinel variant related to emphysema." (PMID 35144588, 2022). "The results suggested that the patients with emphysema carrying the AGER rs2070600 SNP was susceptible to development of CPFE." (PMID 32732977, 2020). "Furthermore, decreased plasma sRAGE in COPD is associated with SNPs in the AGER gene, including G82S, which is also associated with lung function decline and the presence of emphysema." (PMID 37240472, 2023). "Although GWAS revealed the association between AGER gene polymorphisms and emphysema, the underlying pathogenic mechanism is unknown." (PMID 35144588, 2022). "Based on these reports and present results, we suggest that pulmonary fibrosis may occur subsequent to pulmonary emphysema among patients carrying the AGER rs2070600 minor allele (Gly82Ser mutation)." (PMID 32732977, 2020). "Conditional overexpression of AGER in adult murine lungs increased air space enlargement and inflammation similar to COPD, whereas conditional AGER knockout mice were protected from cigarette smoke-induced neutrophil recruitment and emphysema." (PMID 37240472, 2023). "Further studies are needed to prove the temporal relationship between the AGER gene, sRAGE, and emphysema." (PMID 35144588, 2022). "In conclusion, our study showed that the protective effect of plasma sRAGE on emphysema is valid in participants with the CC genotype of rs2070600 on the AGER gene." (PMID 35144588, 2022). "Another of the genes in Community 33, AGER, has been implicated in COPD and encodes sRAGE, a biomarker for emphysema." (PMID 27618581, 2016). "For instance, the minor allele rs2070600 SNP in AGER is associated with lower sRAGE in blood; COPD severity and emphysema extent have also been negatively associated with lower blood sRAGE concentrations in cross-sectional studies." (PMID 27532455, 2016). "Plasma sRAGE might be a biomarker with a protective effect on emphysema among CC-genotyped patients of rs2070600 on the AGER gene." (PMID 35144588, 2022). "Interestingly, rs2070600 and rs2071288 AGER variants have been associated with an increased risk of developing COPD and ARDS or emphysema in COPD patients, respectively." (PMID 34204735, 2021). "Besides, some researchers identified SNP loci associated with peripheral blood protein concentrations by integrating GWAS and proteomics data, such as SNPs in the AGER gene, which may serve as biomarkers for emphysema in COPD." (PMID 39723714, 2025). "Third, the rs2070600 located in AGER, previously reported to be associated with the FEV1/FVC ratio in the European population and associated with COPD, emphysema, and sRAGE levels, was not examined in our study." (PMID 32753590, 2020).
breast carcinoma (16 papers, 2009 to 2025). "A study carried out in northeastern China showed that patients with the AGER gene polymorphism have a 1.6-fold increased risk of developing breast cancer." (PMID 40647480, 2025). "A large cohort of 1904 breast cancer patients from the METABRIC study demonstrated that AGER and the insulin receptor are co-expressed and associated with a worse prognosis." (PMID 40647480, 2025). "Although we did not observe a significant contribution of genetic variants to breast cancer risk, rs2070600 and rs1800624 in the AGER gene were dose-dependently correlated with sRAGE levels." (PMID 36551607, 2022). "AGER expression is linked with advanced-stage breast cancer." (PMID 37511575, 2023). "Moreover, AGER gene SNPs rs2070600 and rs1800624 were correlated with plasma sRAGE level, and the estimated haplotypes TT and TA were remarkably associated with breast cancer risk at the higher quartile of AGEs." (PMID 36551607, 2022). "The relationship among TLR4, AGER, and breast cancer has been documented in BC cell lines and tissue samples." (PMID 40647480, 2025). "AGER has been widely reported to be overexpressed in ovarian cancer, breast cancer, gastric cancer, colorectal cancer, and endometrial cancer." (PMID 29298878, 2018). "In vivo, AGER neutralizing antibody significantly inhibited metastasis development in an established mouse model of lung metastasis and silencing AGER using shRNA markedly reduced metastasis to the lung and liver in multiple xenograft and syngeneic breast cancer mouse models." (PMID 29298878, 2018). "Indeed, AGER has been widely reported being highly expressed in various types of cancer, including ovarian cancer, breast cancer, gastric cancer, and endometrial cancer." (PMID 29298878, 2018). "The activation of the TLR4 and AGER pathways in MCF-7 and MDA-MB-231 breast cancer cell lines promotes β-catenin signaling pathway-activated cell migration." (PMID 40647480, 2025). "Since HMGB1 is overexpressed in breast cancer, TLR4 and AGER assessment offers a broader mechanistic perspective into innate immune activation and damage-associated inflammation, reinforcing the rationale for focusing on these markers." (PMID 40647480, 2025). "This study focuses on two proteins, TLR4 and AGER, which are known to play roles in other types of breast cancer but have not been well-studied in inflammatory breast cancer." (PMID 40647480, 2025). "Notably, AGER expression above the cutoff of 106.7% presented reduced metastatic-free survival, particularly in non-IBC patients, suggesting it could differentially contribute to a worse prognosis depending on the breast cancer subtype." (PMID 40647480, 2025). "However, the impact of the differential expression of TLR4 and AGER on the clinical presentations of BC, such as inflammatory breast cancer (IBC), has not yet been investigated." (PMID 40647480, 2025).
Sepsis (16 papers, 2014 to 2023). Sepsis is defined as life-threatening organ dysfunction caused by a dysregulated host response to infection. "For example, AGER-deficient mice were proven to exhibit protection from lethal polymicrobial sepsis caused by CLP35." (PMID 33436632, 2021). "We next sought to evaluate the impact of using AGER inhibitor FPS-ZM1 or ALOX5 inhibitor zileuton in the development of caspase-11-associated sepsis." (PMID 31440260, 2019). "AGER-mediated lipid peroxidation has been shown to drive caspase-11 inflammasome activation in sepsis, while inflammatory responses in tumor tissue are often favorable for patient prognosis." (PMID 36358600, 2022). "Here, we further showed that AGER promotes caspase-11 inflammasome activation by modulating ALOX5-dependent lipid peroxidation in macrophages during sepsis." (PMID 31440260, 2019). "A previous study showed that the global knockout of AGER protects against sepsis." (PMID 31440260, 2019). "However, AGER is expressed in multiple immune cells (e.g., T cells and macrophages) and we do not understand which of these cells are critical for the phenotypic attenuation of caspase-11 inflammasome activation in sepsis." (PMID 31440260, 2019). "Previous studies demonstrated that a specific inhibition of AGER, MAPK1, MAPK3, and RAF1 signaling reduced the expression of inflammatory cytokines and had beneficial effects during lethal sepsis." (PMID 34948374, 2021).
COVID-19 (15 papers, 2020 to 2025). A disease caused by infection with severe acute respiratory syndrome coronavirus 2. "Thus, it is possible that different AGER variants might differentially predispose patients to COVID-19 comorbidities and dictate the outcome of COVID-19 pathology." (PMID 34204735, 2021). "AGER plays a crucial role in COVID-19-induced lung inflammation, and the AGER pathway represents a therapeutic target for COVID-19 treatment." (PMID 40362649, 2025). "Signature genes associated with AT1 cells, including the reported YAP target genes AGER and CLIC5, were downregulated in COVID-19 patient lung samples." (PMID 40985618, 2025). "This suggests that TOLLIP, TNFRSF4, AGER, and GHRL are crucial inflammatory COVID-19 markers." (PMID 40362649, 2025). "In summary, HMGB1 may be involved in COVID-19 through at least two mechanisms: one is TLR4-mediated cytokine storm in immune cells, and the other is AGER-mediated ACE2 expression in alveolar epithelial cells." (PMID 33313438, 2020).
type 2 diabetes (15 papers, 2013 to 2025). "A genome-wide association (GWA) study of Asian type 2 diabetic patients revealed an association of AGER variants and plasma sRAGE levels, which themselves were associated with diabetic kidney disease." (PMID 30863465, 2019). "AGER is a member of the immunoglobulin superfamily of cell surface molecules, and AGE/AGER interaction has been linked to the regulation of the production/expression of TNF-alpha, oxidative stress, cancer, and endothelial dysfunction in type 2 diabetes." (PMID 34834924, 2021). "However, a recent study reported an ethnicity-dependent contribution of AGER gene in the pathogenesis of diseases, such as type-2 diabetes." (PMID 37110179, 2023). "A meta-analysis did not highlight any significant association between this AGER polymorphism and type 2 diabetes, diabetic retinopathy, or diabetic nephropathy risks." (PMID 30863465, 2019).
chronic obstructive pulmonary disease (14 papers, 2016 to 2024). A chronic and progressive lung disorder characterized by the loss of elasticity of the bronchial tree and the air sacs, destruction of the air sacs wall, thickening of the bronchial wall, and mucous accumulation in the bronchial tree. "Furthermore, AGER (which encodes RAGE) expression, rather than TLR4 expression, was significantly correlated with the sputum neutrophil count and airway hyper-responsiveness in patients with chronic obstructive pulmonary disease (COPD)." (PMID 35626330, 2022).
coronary artery disease (12 papers, 2012 to 2024). "Human studies have also suggested an association of AGEs and its receptor, AGER/RAGE with coronary artery disease in T2DM patients, diabetes-induced ischemic heart disease, and arterial stiffness in type 1 diabetic patients." (PMID 36830898, 2023).
lung diseases (12 papers, 2012 to 2025). "AGER targeted inhibition can improve a variety of lung diseases." (PMID 39896814, 2024). "Based on pathway enrichment analysis, genes altered in BPD blood cells were mainly enriched in cell cycle regulation and arrest (e.g., PPP2CA, RBL2, CENPU, CCNY, CDK6) and pulmonary disorder and developmental disorders (e.g., AGER, ITGA6, CA4, BACH2, IGFBP2, BMPR2, SKI, DAB2)." (PMID 35484630, 2022). "AGER seems to be a modifier gene of lung disease severity in CF, and could be an interesting biomarker of CF airway inflammation." (PMID 22860029, 2012). "Finally, in CF patients, the AGER -374T/A polymorphism leads to the upregulation of RAGE expression and contributes to high IgE levels, and the AGER promoter variant, -429T/C, is associated with more severe lung disease and increased RAGE expression in vitro." (PMID 34204735, 2021). "This study demonstrated that AGER could be a modifier gene of lung disease severity in CF." (PMID 22860029, 2012). "Unlike TLR4, the lung expression of AGER is mainly localized to alveolar epithelial cells and plays an important role in various lung diseases that include viral infections." (PMID 33313438, 2020).